ATP5F1C (ATP synthase F1 subunit gamma)
Description:
Subunit gamma, of the mitochondrial membrane ATP synthase complex (F(1)F(0) ATP synthase or Complex V) that produces ATP from ADP in the presence of a proton gradient across the membrane which is generated by electron transport complexes of the respiratory chain. ATP synthase complex consist of a soluble F(1) head domain - the catalytic core - and a membrane F(1) domain - the membrane proton channel. These two domains are linked by a central stalk rotating inside the F(1) region and a stationary peripheral stalk. During catalysis, ATP synthesis in the catalytic domain of F(1) is coupled via a rotary mechanism of the central stalk subunits to proton translocation (Probable). In vivo, can only synthesize ATP although its ATP hydrolase activity can be activated artificially in vitro (By similarity). With the central stalk subunit delta, is essential for the biogenesis of F(1) catalytic part of the ATP synthase complex namely in the formation of F1 assembly intermediate.
Synonyms: ATP5C; ATP5C1; ATP5CL1
Tractability: Small molecule: a structure with a bound ligand is known. Antibody: UniProt places it where antibodies can reach, with medium confidence. PROTAC: ubiquitination databases record sites on it.
Gene: Protein-coding gene on chromosome 10 (7,788,092 to 7,807,815, forward strand). Ensembl gene ENSG00000165629.
Subcellular location: Mitochondrion inner membrane
Pathways (Reactome):
Metabolism: Formation of ATP by chemiosmotic coupling
Metabolism of proteins: Mitochondrial protein degradation
Organelle biogenesis and maintenance: Cristae formation
Gene Ontology:
Molecular function: protein binding; proton-transporting ATP synthase activity, rotational mechanism; RNA binding; ATP hydrolysis activity
Biological process: proton motive force-driven mitochondrial ATP synthesis; ATP biosynthetic process; oxidative phosphorylation; proton motive force-driven ATP synthesis
Cellular component: membrane; mitochondrion; proton-transporting ATP synthase complex; mitochondrial inner membrane; mitochondrial matrix
Genetic constraint (gnomAD): Loss-of-function variants: 17 observed, 32.57 expected, observed/expected ratio (o/e) 0.52, 90% interval 0.36 to 0.78. The upper end of that interval is the gene's LOEUF score, 0.78, which puts it in group 3 of 6, group 1 being the genes least tolerant of losing a copy. Missense variants: 267 observed, 360.75 expected, observed/expected ratio (o/e) 0.74, 90% interval 0.67 to 0.82. Synonymous variants: 117 observed, 131.29 expected, observed/expected ratio (o/e) 0.89, 90% interval 0.77 to 1.04.
Homologues: Orthologues: chimpanzee ATP5F1C (100% identical), macaque ATP5F1C (98% identical), dog ATP5F1C (96% identical), rabbit ATP5F1C (94% identical), guinea pig ATP5F1C (94% identical), pig ATP5F1C (93% identical), mouse Atp5f1c (91% identical), rat Atp5f1c (81% identical), tropical clawed frog atp5f1c (81% identical), zebrafish atp5f1c (78% identical), Caenorhabditis elegans Y69A2AR.18 (56% identical), Drosophila melanogaster ATPsyngamma (56% identical).
Diseases named in the same sentence as ATP5F1C in open-access papers:
ATP5F1C is named in the same sentence as 24 diseases in open-access papers, as found by Europe PMC text mining. Sharing a sentence is not in itself a finding about the gene and the disease. The quoted sentences say what the papers report.
COVID-19 (2 papers, 2023 to 2025). A disease caused by infection with severe acute respiratory syndrome coronavirus 2. "This study demonstrates that there is a persistent increased activation of nuclear-encoded OXPHOS genes namelyCOX7C, COX7A2, ATP5PO, ATP5F1C and NDUFB8 in blood tissue immediately following COVID-19 recovery, and then a time-dependent tapering off of these genes." (PMID 41141600, 2025). "Interestingly, we also found that ATP synthesis-related genes (e.g., ATP5F1A, ATP5F1B, ATP5F1C, ATP5F1D, ATP5F1E) were significantly increased in COVID-19 patients." (PMID 37087411, 2023).
breast carcinoma (1 paper, 2021). "Briefly, we intersected a series of publicly-available GEO breast cancer DataSets and defined a metastasis-associated gene-signature consisting of five ATP-related genes, namely ATP5F1C, UQCRB, COX20, NDUFA2, and ABCA2." (PMID 34722292, 2021).
invasive breast carcinoma (1 paper, 2021). A carcinoma that infiltrates the breast parenchyma. "In addition, we validated the protein expression of ATP5F1C in female patients with a diagnosis of invasive breast carcinoma (Luminal ER(+) BC, TNBC, HER2(+) BC)." (PMID 33986463, 2021).
metastatic disease (1 paper, 2021). "In summary, we conclude that mitochondrial ATP5F1C is a promising new biomarker and molecular target for future drug development, for the prevention of metastatic disease progression." (PMID 33986463, 2021).
tumor (8 papers, 2012 to 2023). "Moreover, we presented evidence that ATP5F1C is a prognostic biomarker of tumor recurrence and distant metastasis, as well as a marker of treatment failure in ER(+) patients undergoing Tamoxifen therapy." (PMID 33986463, 2021). "Most notably, ATP5F1C (also known as ATP5C1) expression is increased in lymph-node metastases, as compared to the matched primary tumor samples." (PMID 33986463, 2021). "Remarkably, the expression of ATP5F1C and ATP-production, as well as cell growth, remained unaffected after Bedaquiline treatment in MCF-10A cells, a non-tumor-producing human breast epithelial cell line." (PMID 34722292, 2021).
cancer (3 papers, 2020 to 2021). A tumor composed of atypical neoplastic, often pleomorphic cells that invade other tissues. "As a consequence, we conclude that the gamma-subunit of the mitochondrial ATP-synthase (ATP5F1C) is a new therapeutic target, for mitigating aggressive cancer cell behaviors, including spontaneous metastasis." (PMID 33986463, 2021). "Here, we identified ATP5F1C as a clinical biomarker of cancer metastasis." (PMID 33986463, 2021).
metabolic disorder (1 paper, 2022). "In this study, IR significantly increased Atp5flc K55 acetylation levels and Atp5f1c K55-Ac overexpression, which induce metabolic disorder." (PMID 36160705, 2022).
ATP5F1C also shares sentences with these, for which no sentence is quoted: colorectal cancer (4 papers); Parkinson disease (4); neurodegenerative disease (3); Huntington disease (2); prostate carcinoma (2); amyotrophic lateral sclerosis (1); Cognitive impairment (1); diabetes (1); diabetic cardiomyopathy (1); hypertrophic cardiomyopathy (1); mycosis fungoides (1); neuroblastoma (1); Parkinson’s (1); prion disease (1); Sepsis (1); triple-negative breast carcinoma (1); tuberculosis (1).